ENSG00000282034 (novel transcript)
Gene: Protein-coding gene on chromosome 16 (30,704,067 to 30,745,169, forward strand). Ensembl gene ENSG00000282034.
Genetic constraint (gnomAD): Missense variants: 3,413 observed, 4,065.6 expected, observed/expected ratio (o/e) 0.84, 90% interval 0.81 to 0.86. Synonymous variants: 1,675 observed, 1,624.8 expected, observed/expected ratio (o/e) 1.03, 90% interval 0.99 to 1.07.